TUBB (tubulin beta class I)
Diseases named in the same sentence as TUBB in open-access papers (continued):
Sharing a sentence is not in itself a finding about the gene and the disease.
lung adenocarcinoma (3 papers, 2022 to 2024). A carcinoma that arises from the lung and is characterized by the presence of malignant glandular epithelial cells. "In addition, TUBB is the most highly expressed isoform of β-tubulin in most epithelial tumor cells and associates positively with worse prognosis, metastasis, and confers resistance to microtubule-targeting agents in lung adenocarcinoma." (PMID 36140469, 2022). "A high expression of TUBB is correlated with worse survival of lung adenocarcinoma." (PMID 38791306, 2024). "It has been suggested that TUBB might be involved in mediating metastasis in lung adenocarcinoma, possibly through the interaction with miR-195 that targets BIRC5; however the exact mechanism remains to be unclear." (PMID 36140469, 2022).
brain malformations (2 papers, 2015 to 2023). "Diseases associated with TUBB include cortical dysplasia, complex brain malformations, skin Creases, and congenital symmetric circumferential." (PMID 36798127, 2023).
coronary artery disease (2 papers, 2019 to 2022). "Several of these hits including cg18181703 (SOCS3), cg06126421 (TUBB), and cg05575921 (AHRR) were associated with future incidence of coronary heart disease and smoking, whereas two other CpGs were recently identified in an EWAS of type 2 diabetes." (PMID 31205673, 2019). "The associations among the EH domain-binding protein 1 (EHBP1), tubulin beta class I (TUBB), and WW domain-containing oxidoreductase (WWOX) single nucleotide polymorphisms (SNPs) and coronary artery disease (CAD) and ischemic stroke (IS) are not yet understood." (PMID 35559044, 2022).
COVID-19 (2 papers, 2021 to 2025). A disease caused by infection with severe acute respiratory syndrome coronavirus 2. "Despite low expression of ACE2 and other known host factors, olfactory epithelium in COVID-19 patients are reportedly infected with two recent studies using COVID-19 autopsy samples demonstrating that SARS-CoV-2 is detected in OLIG2+ or TUBB(TUJ1)+ oligodendrocytes." (PMID 40674406, 2025).
cutaneous melanoma (2 papers, 2023 to 2024). A primary melanoma arising from atypical melanocytes in the skin. "Furthermore, TUBB was highly expressed in cutaneous melanoma and positively correlated with the malignant behaviour of the tumour such as epithelial-mesenchymal transition (EMT), invasion and metastasis." (PMID 39113897, 2024). "Similarly, silencing LINC00665 inhibits cutaneous melanoma progression via the miR-339-3p/TUBB axis." (PMID 37229449, 2023).
depression (2 papers, 2013 to 2024). "Multivariate logistic regression analysis identified serum ITIH4, C3, C4A and TUBB levels as independent risk factors for depression." (PMID 38895030, 2024). "Multivariate logistic regression analysis revealed that serum levels of TUBB, ITIH4, C3, and C4A were significant independent risk factors for the development of depression." (PMID 38895030, 2024). "Univariate analysis showed that ITIH4, C3, C4A and TUBB levels were significantly different between depression patients and healthy controls." (PMID 38895030, 2024). "The median serum concentrations of TUBB were 110.42 ng/mL and 69.20 ng/mL in depression patients and healthy controls, respectively, with a significant difference between the two groups." (PMID 38895030, 2024). "STRING software showed that ITIH4, C3, C4A and TUBB were involved in the pathogenesis of depression through an unknown pathway." (PMID 38895030, 2024). "The results of the control group ELISA showed that serum levels of TUBB, ITIH4, C3 and C4A were significantly higher in patients with depression than in healthy controls." (PMID 38895030, 2024). "Our study on plasma proteomics for depression demonstrated that TUBB, ITIH4, C3, and C4A differentiate between depression patients and healthy controls." (PMID 38895030, 2024).
dyslipidemia (2 papers, 2021 to 2022). "Our findings revealed that, compared to single-locus effects, TUBB-WWOX-environment interactions can result in synergistic or contrasting effects on incidence of dyslipidemia, thereby increasing or reducing the risk of dyslipidemia." (PMID 33612478, 2021). "In summary, this study identified associations between TUBB, WWOX, environmental factors, serum lipid levels, and dyslipidemia in the Maonan population." (PMID 33612478, 2021). "Among the thirteen TUBB-WWOX interaction types identified, rs3132584T-rs3130685T-rs2222896G-rs2548861T increased the risk of dyslipidemia 1.371-fold." (PMID 33612478, 2021). "In this study, we therefore explored associations between TUBB-WWOX SNPs, their haplotypes, and gene-gene (G × G) and gene-environment (G × E) interactions and the prevalence of dyslipidemia in the Maonan population." (PMID 33612478, 2021). "In addition, multi-site mutations in TUBB and WWOX altered the incidence of dyslipidemia in the Maonan population." (PMID 33612478, 2021). "In this study, we investigated associations between single nucleotide polymorphisms (SNPs) in the tubulin beta class I (TUBB) and WW domain-containing oxidoreductase (WWOX) genes, gene-gene interactions, and gene-environment interactions and dyslipidemia in the Chinese Maonan ethnic group." (PMID 33612478, 2021). "Thirteen TUBB-WWOX G × G interactions were observed in the normal and dyslipidemia groups (LEF for gene interactions > 0.03)." (PMID 33612478, 2021). "This study therefore demonstrated that WWOX haplotype and the combined effects of TUBB × WWOX have larger impacts on serum lipid levels and dyslipidemia than single SNPs in those genes; additional experiments with larger samples sizes are needed to confirm this finding." (PMID 33612478, 2021). "Genotypic and allelic frequencies of TUBB and WWOX SNPs in normal and dyslipidemia groups [n(%)]." (PMID 33612478, 2021).
epilepsy (2 papers, 2020 to 2021). A brain disorder characterized by episodes of abnormally increased neuronal discharge resulting in transient episodes of sensory or motor neurological dysfunction, or psychic dysfunction. "Patient P_000512 with short segment HSCR, epilepsy and intellectual disability, has a large de novo deletion (6p22.1—p21.33) which affects the ENS genes GABBR1, GNL1 and TUBB." (PMID 34358225, 2021).
Intellectual disability (2 papers, 2021 to 2022). "A range of clinical features have been confirmed with heterozygous mutations in Beta Tubulin (TUBB), including skin creases, facial deformities, abnormal cerebral structures, and intellectual disability, and were defined as Circumferential Skin Creases Kunze type (CSC‐KT)." (PMID 35747986, 2022).
liver cancer (2 papers, 2019 to 2022). An epithelial or non-epithelial malignant neoplasm that arises from the liver. "For example, using the data from The Cancer Genome Atlas (TCGA), TUBB expression level influences the survival time of renal and liver cancer." (PMID 30890140, 2019).
neuroblastoma (2 papers, 2021 to 2022). Neuroblastoma (NB) is the most common solid, extracranial childhood tumor. "Moreover, TUBB has been shown to mediate neuroblastoma survival, in which silencing TUBB in differentiated neuroblastoma cells caused apoptosis." (PMID 36140469, 2022). "As microtubule assembly underpins the structural integrity of cells and facilitate cell cycle progression, downregulation of TUBB by MS13 may inhibit cell migration, disrupt cell integrity, and subsequently lead to cell cycle arrest and apoptosis in glioblastoma and neuroblastoma cells." (PMID 33996900, 2021).
ovarian carcinoma (2 papers, 2023). A malignant neoplasm originating from the surface ovarian epithelium. "While MOB1A and CCDC6 were significantly over-expressed in ovarian cancer samples, expression of these genes, as well as of TUBB, PRKAR1A, and SOCS3 appeared to be expressed at high levels in multiple healthy tissue sites." (PMID 36943460, 2023).
prostate carcinoma (2 papers, 2009 to 2012). A carcinoma that arises from epithelial cells of the prostate gland. "Only 1 (a T>C substitution at 30693148 in the 3′UTR of TUBB that was found in two prostate cancer samples) of the 152 (0.66%) somatic mutations in 3′UTRs identified in prostate cancer was found in multiple samples." (PMID 23091610, 2012). "In the gene pairs, our rules indicate that KIAA0762 is downregulated, while TUBB and RGS10 are upregulated in tumor tissue; however, there exists insufficient evidence to directly link the three genes with prostate cancer." (PMID 19874631, 2009).
rheumatoid arthritis (2 papers, 2023). A chronic, systemic autoimmune disorder characterized by inflammation in the synovial membranes and articular surfaces. "In fact, TUBB has been reported to be one of the differentially expressed genes in rheumatoid arthritis." (PMID 36798127, 2023).
acute kidney injury (1 paper, 2025). Sudden and sustained deterioration of the kidney function characterized by decreased glomerular filtration rate, increased serum creatinine or oliguria. "To date, only one in vitro study has demonstrated that the upregulation of TUBB expression can exacerbate inflammation, promote apoptosis, and inhibit autophagy in cases of acute kidney injury." (PMID 40149558, 2025).
acute pancreatitis (1 paper, 2016). An acute inflammatory process that leads to necrosis of the pancreatic parenchyma. "The expression levels of ACTB, TUBB, and B2M were found to be significantly upregulated during acute pancreatitis, whereas the expression level of 18sRNA was downregulated." (PMID 27069927, 2016). "Similar to ACTB, TUBB was not an appropriate reference gene because its expression fluctuated with the pathophysiological process of acute pancreatitis." (PMID 27069927, 2016).
Alagille syndrome (1 paper, 2023). "The molecular diagnosis validated the clinical hypothesis in five patients: hereditary Lymphedema (rWGS_5), mitochondrial depletion syndrome (rWGS_9), Alagille syndrome (rWGS_14), TUBB-related spectrum syndrome (rWGS_18) and 3-hydroxy-3-methylglutaryl-Coa lyase deficiency (rWGS_19)." (PMID 36835410, 2023).
Brown syndrome (1 paper, 2024). Brown syndrome is a rare eye disorder characterized by defects in eye movements caused by abnormalities of the superior oblique tendon sheath of the superior oblique muscle. "Finally, we identified strong candidate variants in additional tubulin-encoding genes TUBB4A in isolated familial Brown syndrome and TUBB in isolated sporadic CFEOM (pedigrees 216, ENG_0678)." (PMID 38585811, 2024).
cholangiocarcinoma (1 paper, 2020). A carcinoma that arises from the intrahepatic biliary tree (intrahepatic cholangiocarcinoma) or from the junction, or adjacent to the junction, of the right and left hepatic ducts (hilar cholangiocarcinoma). "Since there is currently no consensus on the most suitable housekeeping proteins in cholangiocarcinoma, we chose to use GAPDH and TUBB as housekeeping proteins since they are commonly used for this purpose and because suitable peptides were available in the discovery study data." (PMID 32887625, 2020).
ciliopathy (1 paper, 2024). A genetic disorder of the cellular cilia or the cilia anchoring structures, the basal bodies, or of ciliary function. "Furthermore, AlphaFold-based mutagenesis analyses suggest that the ciliopathy-related residue D211 of HYLS1 interacts with the CTT of TUBB and suppresses its inhibitory role in incomplete tubule formation." (PMID 38519454, 2024). "AlphaFold-based structural models and mutagenesis analyses further suggest that the ciliopathy-related residue D211 of HYLS1 physically traps the wobbling C-terminal tail of TUBB, thereby suppressing its inhibitory role in the initiation of the incomplete microtubule assembly." (PMID 38519454, 2024).
cognitive decline (1 paper, 2024). "Seven of the 22 peptides associated with the frail vs control diagnostic contrast and cognitive decline were cytoskeleton-related, including proteoforms of MAP2, VIM, TUBB, DBN1, TUBA8, PALM and NEFM." (PMID 38531951, 2024).
colitis (1 paper, 2025). Inflammation of the colon. "Sera from four patients who developed both skin toxicity and colitis/diarrhea also showed increased autoantibodies to tubulins (TUBB2A, TUBB4A, TUBB, TUBB4B) on treatment." (PMID 40449958, 2025).
colon cancer (1 paper, 2023). "Apart from SPARC, the other genes correlating with immune infiltration included SPOCK1 and INHBA which were highly correlated with CAFs in colon cancer, as well as TUBB (correlations with myeloid dendritic cells in thymoma)." (PMID 36604669, 2023).
deafness (1 paper, 2023). An inherited or acquired condition characterized by the complete loss of the ability to hear from one or both ears. "Another cilia-related transcript is doublecortin-domain containing 2B (DCDC2B, increased 1.9-fold in CAD) which interacts with tubulin 2B (TUBB, increased 1.7-fold in CAD) to affect the hair cell kinocilia, and its mutation likewise leads to recessive deafness." (PMID 37303712, 2023).
diabetes (1 paper, 2023). "Of the top 15 genes presenting differential methylation in both phenotypes, MAD1L1, TUBB, HIST1H2AL and TBCA were significantly associated with diabetes-related phenotypes in the UK Biobank." (PMID 37239390, 2023).
glioma (1 paper, 2021). A benign or malignant brain and spinal cord tumor that arises from glial cells (astrocytes, oligodendrocytes, ependymal cells). "The top 20 co-expressed neighbors were selected, and the core genes PFN1, CALR, thymosin beta 10 (TMSB10), HLA.A, CD74 (HLADG), HLA.DRA, HLA.B, TUBB, and TUBA1A were found to play pivotal roles in the network, suggesting that immune genes are involved in glioma formation." (PMID 34660294, 2021).
intellectual impairment (1 paper, 2022). "Previous studies have shown that two patients with homozygous pathogenic variants in MAPRE2 had severe neurological dysfunction, accompanied by intellectual impairment and seizures, whereas there was no neurological dysfunction in the patients with pathogenic TUBB variants." (PMID 35747986, 2022).
myeloma (1 paper, 2022). "Similarly, we observed that TUBA1B and TUBB regulate the levels and activities of a multitude of myeloma cells working on cell cycle and apoptosis in MM." (PMID 35297204, 2022). "And then, we focus on the TUBA1B and TUBB gene function analysis by knocked‐down in NCI‐H929, RPMI8226 and U266 myeloma cell lines." (PMID 35297204, 2022). "And then, loss‐of‐function experiments with TUBA1B and TUBB knocked‐down in three myeloma cell lines, which illustrated that TUBA1B and TUBB regulated the levels and activities of a multitude of myeloma cells working on cell cycle, cell proliferation and apoptosis in MM." (PMID 35297204, 2022).
ovarian clear cell cancer (1 paper, 2024). An invasive malignant neoplasm that arises from the ovary and is characterized by a predominance of clear and hobnail malignant epithelial cells. "We examined the mRNA and protein expression of ADAMTS19 and TUBB in normal ovarian epithelial IOSE80 cell and ovarian clear cell carcinoma ES-2 cell and ovarian endometrioid carcinoma TOV-112D cell by RT-qPCR and immunohistochemical staining." (PMID 39113897, 2024).
parasite (1 paper, 2024). "Expression profiles revealed significant downregulation of mRNA for proteins ENO1, ACTG1, TUBB, and TUBA3D at 3, 6, and 12 h post parasite infection, respectively." (PMID 38504274, 2024).
schizophrenia (1 paper, 2021). A major psychotic disorder characterized by abnormalities in the perception or expression of reality. "Methylation level at three top-sites was associated with expression levels of genes that have been previously linked to psychiatric or behavioral traits in GWASs: FLOT1 (schizophrenia), TUBB (schizophrenia), and PLXNA2 (general risk tolerance)." (PMID 33420481, 2021).
serous ovarian cancer (1 paper, 2024). "For example, in high-grade serous ovarian cancer, carboplatin induced upregulation of TUBB expression, which affected acquired resistance and cross-resistance in patients." (PMID 39113897, 2024).
uveal melanoma (1 paper, 2014). A melanoma derived from melanocytes of the uveal tract. "TUBB was also reported to be associated with other cancers, and could decrease expression in uveal melanomas that subsequently metastasized compared with those that did not." (PMID 25368985, 2014).
viral infection (1 paper, 2018). "ACT and TUBB are involved in maintaining cytoskeletal structure, and they are found highly modulated during viral infection to facilitate virus internalization and transportation." (PMID 29324904, 2018).